PCDH12 (protocadherin 12)
Description:
Cellular adhesion molecule that may play an important role in cell-cell interactions at interendothelial junctions (By similarity). Acts as a regulator of cell migration, probably via increasing cell-cell adhesion. Promotes homotypic calcium-dependent aggregation and adhesion and clusters at intercellular junctions (By similarity). Unable to bind to catenins, weakly associates with the cytoskeleton (By similarity).
Synonyms: VE-cadherin-2; DMJDS1; VECAD2
Tractability: Antibody: UniProt places it where antibodies can reach, with high confidence; its Gene Ontology location is reachable by antibodies, with high confidence; UniProt predicts a signal peptide or a membrane-spanning region.
Gene: Protein-coding gene on chromosome 5 (141,943,581 to 141,969,741, reverse strand). Ensembl gene ENSG00000113555.
Subcellular location: Cell membrane (Protocadherin-12); Cell junction; Secreted (Protocadherin-12, secreted form)
Gene Ontology:
Molecular function: cell adhesion molecule binding; calcium ion binding
Biological process: calcium-dependent cell-cell adhesion; neuron recognition; cell adhesion; homophilic cell-cell adhesion
Cellular component: extracellular exosome; extracellular region; plasma membrane; anchoring junction; cell-cell junction; membrane
Genetic constraint (gnomAD): Loss-of-function variants: 45 observed, 76.73 expected, observed/expected ratio (o/e) 0.59, 90% interval 0.46 to 0.75. The upper end of that interval is the gene's LOEUF score, 0.75, which puts it in group 3 of 6, group 1 being the genes least tolerant of losing a copy. Missense variants: 1,369 observed, 1,566.2 expected, observed/expected ratio (o/e) 0.87, 90% interval 0.83 to 0.91. Synonymous variants: 566 observed, 658.69 expected, observed/expected ratio (o/e) 0.86, 90% interval 0.8 to 0.92.
Homologues: Orthologues: chimpanzee PCDH12 (99% identical), macaque PCDH12 (98% identical), dog PCDH12 (87% identical), pig PCDH12 (86% identical), rabbit PCDH12 (81% identical), mouse Pcdh12 (80% identical), rat Pcdh12 (80% identical), guinea pig PCDH12 (70% identical), zebrafish pcdh12 (41% identical). Paralogues in human: PCDH18 (26% identical), PCDH17 (26% identical), PCDH10 (25% identical), PCDHGA2 (24% identical), PCDH19 (24% identical), PCDHGA6 (24% identical), PCDHGA5 (24% identical), PCDHB10 (23% identical), PCDHGA1 (23% identical), PCDHGA3 (23% identical), PCDHGA9 (23% identical), PCDHGA12 (23% identical), and 49 more.
Diseases named in the same sentence as PCDH12 in open-access papers:
PCDH12 is named in the same sentence as 24 diseases in open-access papers, as found by Europe PMC text mining. Sharing a sentence is not in itself a finding about the gene and the disease. The quoted sentences say what the papers report.
schizophrenia (4 papers, 2011 to 2021). A major psychotic disorder characterized by abnormalities in the perception or expression of reality. "For example, PCDH10 mutations have been linked to autism, PCDH12 mutations have been associated with schizophrenia and microcephaly and seizures, and PCDH17 mutations have been involved in the pathogenesis of schizophrenia." (PMID 34201522, 2021). "Genome association studies have shown that single-nucleotide polymorphisms and deletions in Pcdh genes, such as PCDH10, PCDH11Y and PCDH12, are associated with bipolar disorder, schizophrenia and autism, respectively." (PMID 21824415, 2011). "Moreover, a group of cadherins, CDH7, CDH12, CDH18 and PCDH12, are reported to be associated with bipolar disease and schizophrenia." (PMID 30148849, 2018).
microcephaly (3 papers, 2021 to 2025). A congenital or acquired developmental disorder in which the circumference of the head is smaller than normal for the person's age and sex. "PCDH12 variants have been associated with schizophrenia, and bi-allelic pathogenic variants lead to seizures, microcephaly, and white matter abnormalities." (PMID 40870033, 2025). "Another example is the Pcdh12 null mice, also reported to be viable and show no morphological abnormalities, while the patients carrying bi-allelic pathogenic variants present with seizures, microcephaly, and white matter abnormalities." (PMID 40870033, 2025).
psychosis (2 papers, 2017 to 2021). "The 26th ranked gene PCDH12 was previously associated with brain calcifications, which could cause memory loss, personality changes, and diminished intellectual function, thereby potentially leading to psychosis or neurocognitive disorder." (PMID 34492068, 2021).
atherosclerosis (1 paper, 2025). A disease characterized by the build-up of fatty material and calcium deposition in the arterial wall resulting in partial or complete occlusion of the arterial lumen. "In our study, we identified APLNR, PCDH12, PODXL, SLC40A1, TM4SF18, and TNFRSF25 as the most relevant genes associated with lipid metabolism and atherosclerosis, highlighting their potential as diagnostic and immune markers." (PMID 40070840, 2025). "Through further differential analysis and screening using machine learning algorithms, APLNR, PCDH12, PODXL, SLC40A1, TM4SF18, and TNFRSF25 were identified as key diagnostic genes for atherosclerosis." (PMID 40070840, 2025). "We determined that APLNR, PCDH12, PODXL, SLC40A1, TM4SF18, and TNFRSF25 are key genes associated with lipid metabolism in samples affected by atherosclerosis." (PMID 40070840, 2025). "Our study employed various machine learning algorithms to identify that APLNR, PCDH12, PODXL, SLC40A1, TM4SF18, and TNFRSF25, among the lipid metabolism genes, can serve as diagnostic markers in patients with atherosclerosis and are associated with atherosclerotic immune infiltration." (PMID 40070840, 2025). "Through our investigation, we discerned the crucial functions of APLNR, PCDH12, PODXL, SLC40A1, TM4SF18, and TNFRSF25 within the framework of atherosclerosis." (PMID 40070840, 2025). "The ROC curve was employed to assess the predictive potential of these key gene markers in atherosclerosis, revealing that the AUC values for APLNR, PCDH12, PODXL, SLC40A1, TM4SF18, and TNFRSF25 were 0.763, 0.859, 0.780, 0.807, 0.792, and 0.848, respectively." (PMID 40070840, 2025).
breast carcinoma (1 paper, 2022). "The expressions of PCDH12, SLIT3, ACVRL1 and DLL4 not merely relate to the type and proportion of immune cells, but also contribute to the prognosis of breast cancer." (PMID 35953532, 2022).
colorectal adenocarcinoma (1 paper, 2018). The most common type of colorectal carcinoma. "For example, the P1772S variant in the HELZ2 gene is present in cutaneous melanoma and colorectal adenocarcinoma, the C1183S variant in PCDH12 is present in renal cell carcinoma and colorectal adenocarcinoma." (PMID 30301885, 2018).
Dystonia (1 paper, 2021). An abnormally increased muscular tone that causes fixed abnormal postures.
fetal growth restriction (1 paper, 2025). A fetus that does not grow beyond the 10th percentile of conventionally accepted weight for gestational age. "PCDH12, in particular, has been shown to play a pivotal role in endothelial–trophoblast interaction and vascular remodeling, while cadherins and nectin dysregulation has been associated with fetal growth restriction and pre-eclampsia." (PMID 41614738, 2025).
lymph node metastasis (1 paper, 2022). "The results suggest that the expression of ECM2, PCDH12, EPAS1, CD93, DLL4, and ARHGEF15 are significantly different in age, N (lymph node metastasis status), and whether radiotherapy is received or not." (PMID 35953532, 2022).
nonsyndromic hearing loss (1 paper, 2021). "Rare biallelic variants in PCDH12 (OMIM 605622) and PCDH15 (OMIM 605514) have been reported in patients with diencephalic–mesencephalic junction dysplasia syndrome 1 (DMJDS1; OMIM 251280), Usher syndrome type 1F (USH1F, OMIM 602083), and nonsyndromic hearing loss (DFNB23; OMIM 609533), respectively." (PMID 34244665, 2021).
retinal degeneration (1 paper, 2017). Degeneration of the retina. "They include genes involved in nuclear trafficking and gene silencing (IPO8), fast axonal guidance and synaptic specificity (PCDH12), transduction of nerve signals (NRSN1), retinal degeneration (LMO7), synaptic glutamate release (SH3GL2), and broader nervous system development and function." (PMID 29064472, 2017).
trisomy 16 (1 paper, 2022). "Among the DMGs in miscarriages with trisomy 16, two genes (FOSL1 and PCDH12) were involved in placental development (GO:0001890)." (PMID 35064135, 2022).
cancer (1 paper, 2018). A tumor composed of atypical neoplastic, often pleomorphic cells that invade other tissues. "In contrast, some of the genes, including ENTHD1, HELZ2, PCDH12, CPNE4, and SHANK1, that are mutated in metastatic ACCs alone are completely novel and have not been functionally characterized in any cancer type until now." (PMID 30301885, 2018).
tumour (1 paper, 2008). "Of these, angiopoietin 2 (ANGPT2), protocadherin 12 (PCDH12) and leucine rich repeat containing 8 family member C (LRRC8C) had expression profiles completely restricted to tumour or foetal tissues." (PMID 18394197, 2008).
PCDH12 also shares sentences with these, for which no sentence is quoted: autism (2 papers); bipolar disorder (1); cutaneous melanoma (1); Hypotonia (1); Macrocephaly (1); Myoclonus (1); neurological disease (1); renal cell carcinoma (1); Tremor (1); Usher syndrome type 1F (1).